APBB1IP (amyloid beta precursor protein binding family B member 1 interacting protein)
Description:
Appears to function in the signal transduction from Ras activation to actin cytoskeletal remodeling. Suppresses insulin-induced promoter activities through AP1 and SRE. Mediates Rap1-induced adhesion.
Synonyms: RIAM; PREL1; RARP1; INAG1
Tractability: Antibody: its Gene Ontology location is reachable by antibodies, with high confidence; UniProt places it where antibodies can reach, with medium confidence; the Human Protein Atlas places it where antibodies can reach. PROTAC: ubiquitination databases record sites on it; its protein half-life has been measured.
Gene: Protein-coding gene on chromosome 10 (26,438,341 to 26,568,449, forward strand). Ensembl gene ENSG00000077420.
Subcellular location: Cell membrane; Cell projection, lamellipodium; Cell junction, focal adhesion; Cytoplasm, cytoskeleton
Subcellular location (Human Protein Atlas): Cytosol; Plasma membrane
Pathways (Reactome):
Disease: Paradoxical activation of RAF signaling by kinase inactive BRAF; Signaling by BRAF and RAF1 fusions; Signaling by RAF1 mutants; Signaling by high-kinase activity BRAF mutants; Signaling by moderate kinase activity BRAF mutants; Signaling downstream of RAS mutants
Signal Transduction: GRB2:SOS provides linkage to MAPK signaling for Integrins; Integrin signaling; MAP2K and MAPK activation; p130Cas linkage to MAPK signaling for integrins
Gene Ontology:
Molecular function: protein binding; protein-macromolecule adaptor activity
Biological process: intracellular signal transduction; signal transduction
Cellular component: cytosol; plasma membrane; cytoskeleton; focal adhesion; lamellipodium; T cell receptor complex
Genetic constraint (gnomAD): Loss-of-function variants: 21 observed, 51.73 expected, observed/expected ratio (o/e) 0.41, 90% interval 0.29 to 0.58. The synonymous counts are far from expectation, so gnomAD's model fits this gene poorly and the ratio says little. Missense variants: 679 observed, 678.96 expected, observed/expected ratio (o/e) 1, 90% interval 0.94 to 1.07. Synonymous variants: 322 observed, 262.29 expected, observed/expected ratio (o/e) 1.23, 90% interval 1.12 to 1.35.
Homologues: Orthologues: chimpanzee APBB1IP (98% identical), macaque APBB1IP (95% identical), pig APBB1IP (85% identical), dog APBB1IP (84% identical), mouse Apbb1ip (81% identical), guinea pig APBB1IP (75% identical), tropical clawed frog apbb1ip (59% identical), zebrafish apbb1ip (52% identical), Drosophila melanogaster pico (31% identical), Caenorhabditis elegans mig-10 (29% identical). Paralogues in human: RAPH1 (48% identical), GRB10 (21% identical), GRB14 (20% identical), GRB7 (17% identical).